ACHE (acetylcholinesterase (Yt blood group))
Diseases named in the same sentence as ACHE in open-access papers (continued):
Sharing a sentence is not in itself a finding about the gene and the disease.
infection (continued). "Acetylcholinestrase (AChE) activities increased during the entire experimental period, whereas those of superoxide dismutase (SOD), peroxidase (POD) and catalase (CAT) decreased during the later infection period." (PMID 28425450, 2017). "BuChE performance was observed when AChE was suppressed, with increased activity in the GAL/INF group similar to the INF group on the 30th day post infection, thus corroborating the absence of a significant difference in parasitic curves and histopathological analysis." (PMID 34787259, 2021).
metabolic disorders (13 papers, 2015 to 2025). "Neurodegeneration is associated with increased acetylcholinesterase (AChE) levels, metabolic disorders, the formation of amyloid-beta plaques, and intracellular neurofibrillary tangles." (PMID 39942962, 2025). "When the enzyme inhibition results were evaluated and compared with standard inhibitors, cinnamon leaf oil was found to have an effective inhibition capacity against AChE, α-amylase, and hCA II, which are associated with global metabolic diseases, such as AD and T2DM." (PMID 36676085, 2023). "The regulatory effects of fatty acids on BChE and AChE emphasize their potential as therapeutic targets for neurological and metabolic diseases." (PMID 40116876, 2025). "The inhibitory effects of ML extract on AChE, BChE, and α‐glucosidase enzymes were also investigated, demonstrating the therapeutic potential of mango leaves in addressing neurodegenerative and metabolic diseases." (PMID 40351366, 2025). "Among its constituents, spathulenol emerged as a key bioactive compound, demonstrating strong binding affinities with multiple therapeutic targets such as AChE, BChE, α-glucosidase, and α-amylase, suggesting its potential as a dual-action agent in managing neurodegenerative and metabolic disorders." (PMID 41191233, 2025).
brain disorder (6 papers, 2017 to 2024). A disease affecting the brain or part of the brain. "Loss of brain AChE activity is evident in several brain disorders including neurodegenerative diseases." (PMID 29263397, 2017). "Mounting evidence has shown reduced activity of AChE in several brain disorders, including neurodegenerative disorders." (PMID 29263397, 2017). "However, some macrocyclic and open-chain spermine and spermidine alkaloids have exhibited great potential for the treatment of brain diseases by inhibiting the activities of AChE and BuChE." (PMID 38732396, 2024). "Although the essential etiological factor for AD has not yet been identified, the hallmarks of this disorder are recognized abnormal brain diseases, such as the over-expression of Acetylcholinesterase (AChE) and the extracellular deposition of “mystery”-amyloid plaques." (PMID 36678724, 2022). "Increasing data indicate decreased AChE activity in numerous brain disorders, including PD and AD." (PMID 35068069, 2022).
cardiovascular disease (5 papers, 2016 to 2024). "Accumulating evidence suggests that parasympathetic augmentation through inhibition of AChE with PYR may provide a non‐invasive therapeutic option for cardiovascular disease." (PMID 33755308, 2021).
cardiac disease (4 papers, 2021 to 2024). "Cardiac acetylcholine which can be hydrolyzed to acetate and choline by acetylcholinesterase (AchE) plays critical functions in regulating changes in cardiac rate and contractility and plays protective roles in cardiac diseases." (PMID 35841183, 2023). "Further studies are needed to define the prevailing mechanisms of the beneficial effects, and the therapeutic efficacy of AChE inhibitors is needed to support their use in patients with cardiac disease." (PMID 33755308, 2021). "Although modulation of cardiac autonomic activity using acetylcholinesterase (AChE) inhibitors, including donepezil and pyridostigmine, has been demonstrated to exert cardioprotection in many heart diseases, the anti-cardiotoxic effects of donepezil against TIC remain largely unknown." (PMID 37691124, 2023).
central nervous system disorder (3 papers, 2012 to 2021). A disease involving the central nervous system. "In Senegal, leaves and bulbs of P. trianthum are used to treat central nervous system disorder, heal wounds, and soothe irritations, suggesting potential anti-AChE, antibacterial, and antiviral activity." (PMID 34885964, 2021). "Based on the traditional use of the Pancratium genus for wound-healing, central nervous system disorder, and antiproliferative and antiviral purposes, the alkaloid extracts prepared were screened for antibacterial, anti-AChE, cytotoxic, and antiviral properties." (PMID 34885964, 2021).
myopathy (3 papers, 2011 to 2022). A disease of the muscle in which the muscle fibers do not function properly. "It is known that in ache mutants the lack of AChE activity can cause a progressive myopathy in zebrafish embryos." (PMID 22205996, 2011). "It is known that the lack of AChE activity in zebrafish results in an increase of muscular activity and can cause a progressive myopathy." (PMID 22205996, 2011). "Indirect evidence for the role of calcium ions is provided by studies that demonstrate a rescue of myopathy (provoked by exposure to AChE inhibitors) by calcium channel blockers." (PMID 22205996, 2011). "Prolonged AChE inhibition or complete lack of AChE results in an accumulation of ACh and overstimulation of the muscle, leading to spasms and myopathy-like phenotypes." (PMID 22205996, 2011).
bacterial infections (2 papers, 2018 to 2023). "Therefore, the two genes analyzed in relation to the nervous system (AChE) and immunity (ApA) showed some alteration, suggesting some mid-term effects on the physiology of P. acuta could occur such as feed searching behaviour or susceptibility to bacterial infections." (PMID 36899054, 2023). "Therefore, we can conclude that the inhibition of AChE increases resistance to oral but not systemic bacterial infections." (PMID 29616040, 2018).
gastrointestinal disorders (2 papers, 2019 to 2020). "Interestingly, Mentha extracts showed anti-acetylcholinesterase activity and the reversible inhibition of AChE activity has been proposed for the treatment of various diseases, including gastrointestinal disorders and Alzheimer’s disease." (PMID 31247911, 2019).
respiratory diseases (2 papers, 2019 to 2023). "The major pathophysiological pathways through which OP exposure might promote the risk of respiratory diseases include the inhibition of AChE and accumulation of Ach, which might induce overstimulation throughout the central and peripheral nervous systems." (PMID 37755752, 2023).
digestive system cancer (1 paper, 2014). A primary or metastatic malignant neoplasm involving any part of the digestive system. "Our work demonstrated for the first time that AChE gene mediated by an oncolytic adenovirus is effective for suppressing digestive system cancers." (PMID 25220382, 2014).
immune system diseases (1 paper, 2014). "The therapeutic agents can thus be targeted to the AChE protein, its encoding mRNA transcripts, or the regulator, opening new venues for therapeutic interference with immune system diseases." (PMID 24733966, 2014).
mitochondrial disease (1 paper, 2023). "Some patients with mitochondrial disease responded to AChE inhibitors, indicating they may be amenable to treatments targeting NMJ dysfunction." (PMID 37239850, 2023).
neurodevelopmental disorder (1 paper, 2020). A behavioral and cognitive disorder with onset during the developmental period that involves impaired or aberrant development of intellectual, motor, or social functions. "But whether developmental exposure to CPF at levels that do not significantly inhibit acetylcholinesterase (AChE) causes phenotypes of relevance to neurodevelopmental disorders remains unclear." (PMID 33327943, 2020).
neuromuscular disease (1 paper, 2015). "The release of AChE may help promote the growth of nervous tissue, avoid enteric neuromuscular disease, which is a type of colonic pseudoobstruction, and prevent the development of constipation." (PMID 25452815, 2015).
ACHE also shares sentences with these, for which no sentence is quoted: Parkinson (16 papers); atherosclerosis (3); Coma (3); multiple sclerosis (3); neurotoxicity (3); amyotrophic lateral sclerosis (2); Arrhythmia (2); astrocytoma (2); autism spectrum disorder (2); essential hypertension (2); frontotemporal dementia (2); gout (2); incontinence (2); Jaundice (2); liver dysfunction (2); lupus (2); muscular disorders (2); rheumatoid arthritis (2); Thiamine deficiency (2); acanthosis nigricans (1); acne (1); acute coronary syndrome (1); acute myocardial infarction (1); acute respiratory failure (1); Adult onset (1); Atrophy (1); benign brain tumors (1); cardiac arrest (1); cardiac arrhythmia (1); cardiac hypertrophy (1).
A further 68 diseases each share a sentence with ACHE in 1 paper.